SP7 (Sp7 transcription factor)
Description:
Transcriptional activator essential for osteoblast differentiation. Binds to SP1 and EKLF consensus sequences and to other G/C-rich sequences (By similarity).
Synonyms: OSX; osterix; OI11; OI12
Tractability: PROTAC: UniProt records ubiquitination sites on it; ubiquitination databases record sites on it.
Gene: Protein-coding gene on chromosome 12 (53,326,575 to 53,345,315, reverse strand). Ensembl gene ENSG00000170374.
Subcellular location: Nucleus
Pathways (Reactome):
Gene expression (Transcription): RUNX2 regulates osteoblast differentiation
Gene Ontology:
Molecular function: protein binding; DEAD/H-box RNA helicase binding; DNA binding; DNA-binding transcription activator activity, RNA polymerase II-specific; DNA-binding transcription factor activity, RNA polymerase II-specific; RNA polymerase II cis-regulatory region sequence-specific DNA binding
Biological process: hematopoietic stem cell differentiation; osteoblast differentiation; positive regulation of stem cell differentiation; positive regulation of transcription by RNA polymerase II; regulation of transcription by RNA polymerase II; cellular response to parathyroid hormone stimulus; cellular response to zinc ion starvation; response to insulin; response to mechanical stimulus
Cellular component: cytoplasm; nucleus; chromatin
Genetic constraint (gnomAD): Loss-of-function variants: 12 observed, 24.07 expected, observed/expected ratio (o/e) 0.5, 90% interval 0.32 to 0.81. The upper end of that interval is the gene's LOEUF score, 0.81, which puts it in group 3 of 6, group 1 being the genes least tolerant of losing a copy. Missense variants: 442 observed, 501.79 expected, observed/expected ratio (o/e) 0.88, 90% interval 0.81 to 0.95. Synonymous variants: 187 observed, 202.62 expected, observed/expected ratio (o/e) 0.92, 90% interval 0.82 to 1.04.
Homologues: Orthologues: chimpanzee SP7 (99% identical), macaque SP7 (99% identical), pig SP7 (97% identical), rabbit SP7 (95% identical), mouse Sp7 (94% identical), rat Sp7 (94% identical), guinea pig SP7 (94% identical), zebrafish sp7 (61% identical), tropical clawed frog sp7 (58% identical), Caenorhabditis elegans sptf-1 (15% identical), Drosophila melanogaster luna (14% identical). Paralogues in human: SP8 (45% identical), SP9 (43% identical), SP6 (30% identical), SP5 (28% identical), KLF11 (22% identical), KLF10 (21% identical), KLF13 (19% identical), KLF5 (19% identical), KLF14 (17% identical), KLF4 (17% identical), KLF15 (17% identical), KLF16 (17% identical), and 10 more.
Diseases named in the same sentence as SP7 in open-access papers:
SP7 is named in the same sentence as 34 diseases in open-access papers, as found by Europe PMC text mining. Sharing a sentence is not in itself a finding about the gene and the disease. The quoted sentences say what the papers report.
osteogenesis imperfecta (12 papers, 2020 to 2025). Osteogenesis imperfecta (OI) comprises a heterogeneous group of genetic disorders characterized by increased bone fragility, low bone mass, and susceptibility to bone fractures with variable severity. "Aberrant expression or mutations in the SP7 gene can lead to conditions like osteoporosis and osteogenesis imperfecta." (PMID 40231202, 2025). "For instance, recessive osteogenesis imperfecta, characterized by bone fragility and delayed motor milestones, can result from frameshift mutations in SP7." (PMID 40231202, 2025). "Mutations in SP7 have been identified as a rare cause of osteogenesis imperfecta (OI type XII) in one case of juvenile Paget’s disease." (PMID 35628456, 2022). "Mutations in SP7 cause recessive osteogenesis imperfecta (OI type XII), characterized by generalized osteopenia, recurrent fractures, bone deformities and bent bones." (PMID 34465741, 2021). "Homozygous mutations in SP7/Osterix have been linked to type XII osteogenesis imperfecta (OMIM #613849) characterized by skeletal anomalies including repeated bone fractures, generalized osteoporosis, and mild bone deformities." (PMID 33207791, 2020). "Similarly, pathogenic variants in SP7 in humans have been described only in recessive osteogenesis imperfecta (OI type XII) with generalized osteoporosis." (PMID 35121733, 2022). "This is the case of sp7 −/− zebrafish mutants which have the deletion of all three zinc-finger domains of Sp7 and are a model of a severe recessive form of human osteogenesis imperfecta (type XII, OMIM# 613849) which, instead, is characterized by the deletion of only the last zinc-finger domain." (PMID 32824602, 2020).
Osteopenia (8 papers, 2012 to 2025). Osteopenia is a term to define bone density that is not normal but also not as low as osteoporosis. "SIRT7 knockout displayed severe osteopenia by regulating lysine acylation of SP7/Osterix to decrease bone formation and increase osteoclasts." (PMID 41184233, 2025). "S1PR2 regulates the expression of Osterix (Sp7), a key transcription factor in osteoblastogenesis resulting in osteopenia in S1PR2 knockout mice." (PMID 38477738, 2024). "Osteopenia-specific Sirt7 knockout mice showed decreased bone formation that occurred via acylation of SP7/Osterix (OSX)—a transcription factor that activates genes involved in osteoblast differentiation." (PMID 34129782, 2021). "Sp7 transgenic mice under the control of 2.3 kb Col1a1 promoter showed osteopenia and woven-bone like structure in the cortical bone, which was thin and less mineralized, in a dose-dependent manner." (PMID 22396760, 2012). "Further, the osteopenia in Sp7 or Runx2 transgenic mice was worsened in Sp7/Runx2 double transgenic mice and the expression of Col1a1 and Bglap2 was reduced." (PMID 22396760, 2012). "Osteoblast-specific Sp7 transgenic mice showed osteopenia due to the inhibition of osteoblast differentiation at a late stage, and SP7 positively regulated its own promoter." (PMID 22396760, 2012). "Further, osteoblast-specific deletion of Sp7 resulted in osteopenia due to the inhibition of osteoblast differentiation in adult mice." (PMID 22396760, 2012). "Given that overexpression of Sp7 in osteoblasts using a transgenic approach resulted in osteopenia with suppression of osteoblast differentiation, an appropriate dosage of Sp7 may be required for the proper execution of the osteoblast program in adults." (PMID 35628456, 2022).
osteoporosis (8 papers, 2019 to 2025). A condition of reduced bone mass, with decreased cortical thickness and a decrease in the number and size of the trabeculae of cancellous bone (but normal chemical composition), resulting in increased fracture incidence. "Although the number of each cell types exhibited no statistically calculated difference, the number of Bglap+ and Sp7+ cells in osteoporosis showed a decreasing tendency, which also implicated OB differentiation blockage in osteoporosis." (PMID 40051391, 2025). "Dysregulation of Sp7 is also linked to osteoporosis, a condition characterized by low bone mass density." (PMID 40231202, 2025). "Predicting SP7 sequences is crucial for understanding bone development, osteoporosis, regenerative medicine, drug development, evolutionary studies, and biomarker identification." (PMID 40231202, 2025). "miR-381-3p negatively correlated with CTD-2555A7.2 expression and osteogenic marker genes, such as Ocn and Sp7, in osteoporosis patients with advanced age." (PMID 40593084, 2025). "To mimic osteoporosis progression in patients, we used the zebrafish larva glucocorticoid-induced osteoporosis model, which is labeled with the stable fluorescent protein Sp7." (PMID 36599933, 2023). "Gene assays in the osteoporotic zebrafish model revealed that LC86 significantly boosted the expression of crucial bone metabolism genes, such as sp7, runx2a, bmp2a, bmp4, and col2a1a, which are vital for bone formation, mineralization, and osteoporosis pathogenesis." (PMID 40308595, 2025). "SP7/OSTERIX has been associated to OI, Paget’s bone disease and osteoporosis by GWAS." (PMID 34938269, 2021).
breast carcinoma (3 papers, 2020 to 2025). "In addition, SP7 was associated with lymphatic metastasis and poorer survival in breast cancer." (PMID 34367994, 2021). "Upregulation of Sp7 in breast cancer cells is associated with increased invasion and bone metastasis, and this may occur by upregulation of ECM modifying metalloproteinases, MMP9 and MMP13, and other factors that increase vascularization, and affect bone cell function." (PMID 32755539, 2020). "It has been revealed that SP7 can promote lymph node metastasis of breast cancer, promote angiogenesis, reduce the sensitivity of chemotherapy and have a worse prognosis." (PMID 34367994, 2021).
periodontitis (3 papers, 2015 to 2024). An acute or chronic inflammatory process that affects the tissues that surround and support the teeth. "We found that periodontitis-induced bone loss and osteoclast number were markedly suppressed when RANKL was deleted in osteoblastic cells (Sp7-Cre) and periodontal ligament cells (Scx-Cre)." (PMID 29453398, 2018). "To investigate the importance of OSMR signaling in osteogenic cells in periodontitis-induced bone damage in vivo, we crossed OSMR-floxed mice with Sp7-Cre mice." (PMID 38413562, 2024). "The two most down-regulated genes in periodontitis were keratin 71 (KRT71) and SP7 (fold change <−10 in both cases), of which the latter was also identified by the OPLS-DA." (PMID 26686060, 2015).
craniosynostosis (2 papers, 2022 to 2025). Craniosynostosis is defined as the premature fusion of one or more cranial sutures leading to secondary distortion of skull shape resulting in skull deformities with a variable presentation. "Given that the genes near many of the loci identified in our pleiotropy-informed GWAS are directly or indirectly related to RUNX2 or SP7, it is possible that together they can predict a considerable proportion of craniosynostosis risk." (PMID 40087503, 2025). "Given the close link between many of the identified loci and the master regulators of suture ossification, RUNX2 and SP7, it is plausible that collectively our loci comprise a polygenic background predictive of craniosynostosis risk and severity." (PMID 40087503, 2025). "Interestingly, genes that likely induce RUNX2 or SP7 expression tend to cause craniosynostosis through gain-of-function mutations or whole gene duplications, such as MSX2101,102, LRP585, SOX11103, IHH104, and RUNX2 itself." (PMID 40087503, 2025).
hypospadias (2 papers, 2019 to 2020). Hypospadias is the displacement of the urethral meatus on the ventrum of the penis. "To further interpret the potential mechanism regulated by SP1 and SP7, we investigated these two genes and previous reported hypospadias risk associated genes by PPIs analysis using GeneSense and STRING." (PMID 31856834, 2019). "So if SP1 or SP7 interacts with one of the proteins encoded by a hypospadias risk gene, it is likely to interact (indirectly) with many of the proteins encoded by hypospadias risk genes." (PMID 31856834, 2019). "We identified rs11170516 with the risk allele G within the SP1/SP7 region that was independently associated with moderate-severe hypospadias [SP1/SP7, rs11170516, Pcombine = 3.5 × 10− 9, odds ratio (OR) = 1.96 (1.59–2.44)]." (PMID 31856834, 2019). "Although we did not include all possible proteins encoded by hypospadias risk associated genes (for example IRX5, IRX6, EYA1) for PPIs, our investigations indicated that disruption of SP1 and SP7 activity is associated with multiple known hypospadias risk associated genes in human via PPIs." (PMID 31856834, 2019).
osteoarthritis (2 papers, 2022 to 2024). A noninflammatory degenerative joint disease occurring chiefly in older persons, characterized by degeneration of the articular cartilage, hypertrophy of bone at the margins and changes in the synovial membrane. "BMP-2 and SP7 are two positive regulators of chondrocyte hypertrophy and are both reported to be upregulated in osteoarthritis cartilages." (PMID 35280506, 2022).
osteosarcoma (2 papers, 2021 to 2023). A usually aggressive malignant bone-forming mesenchymal neoplasm, predominantly affecting adolescents and young adults. "More interestingly, the expression of several of these genes, including CHST13, FKBP11, SGMS2, TRPS1, PRKX, SP7, and DNAJC1, were highly associated with osteosarcoma prognosis." (PMID 37457661, 2023). "The genes of four TFs (DDIT3, SP7 and CREB3L1) were significantly activated in C5_osteoblastic OS cells, and these TFs have been shown to be expressed in osteosarcoma in previous studies." (PMID 34367994, 2021).
cyst (1 paper, 2014). A sac-like closed membranous structure that may be empty or contain fluid or amorphous material. "Its reduced expression in Sp7-flcAΔ under flocculation conditions emphasized the involvement of the CheW-homologous gene in the transformation of Azospirillum from vegetative to cyst-like cells." (PMID 25502569, 2014). "Nutritional stress under flocculation conditions is aggravated in Sp7-flcAΔ as the cells are unable to fully respond to this stress by normal transformation into cyst-like, relatively dormant forms." (PMID 25502569, 2014).
endothelial dysfunction (1 paper, 2025). In vascular diseases, endothelial dysfunction is a systemic pathological state of the endothelium (the inner lining of blood vessels) and can be broadly defined as an imbalance between vasodilating and vasoconstricting substances produced by (or acting on) the endothelium. "The set includes genes such as CLDN18, NOS2, SLC4A1, CA4, COL17A1, and SP7, many of which have been implicated in vascular inflammation, endothelial dysfunction, and extracellular matrix remodelling." (PMID 41226477, 2025).
hepatoma (1 paper, 2021). "Those constructs were transfected in human hepatoma cells (Huh-7) in parallel with native human FGF23 and wild-type (WT) and codon-optimized versions of cFGF23 coding DNA fused with the FGF23 native signal peptide or sp7." (PMID 34705504, 2021).
hypophosphatemic rickets (1 paper, 2019). Rickets due to low serum phosphate concentrations, the cause of which can be nutritional or genetic. "However, Von Kossa stained sections from Sp7-Cre;SMS1f/f;SMS2−/− mice did not demonstrate characteristic features of hypophosphatemic rickets including increased width of the unmineralized epiphyseal growth plate and increased trabecular bone volume in the proximal metaphysis." (PMID 31847800, 2019).
knee osteoarthritis (1 paper, 2022). "Here, we found that Dlx5, SP7, and BMP-2 were all increased in papain-induced knee osteoarthritis, and upregulation of SP7 and BMP-2 were partly dependent on Dlx5." (PMID 35280506, 2022).
latent infection (1 paper, 2024). "Strikingly, the protection conferred against M. robertsii by the prior ingestion of PAO1 was abolished in the ΔPPO1-ΔPPO2 and Hayan mutants, but not in the Sp7 mutants, even though the latter are much more sensitive than Hayan to the PAO1 latent infection protocol." (PMID 38833496, 2024).
Obesity (1 paper, 2016). Accumulation of substantial excess body fat. "Consistent with these previous reports, obesity may have a role in inhibiting downstream regulatory activity of sp7 and reducing the ability of sp7 to induce osteonectin and COLA1a expression." (PMID 26818763, 2016).
scoliosis (1 paper, 2024). A congenital or acquired spinal deformity characterized by lateral curvature of the spine. "Mutations in SP7 lead to OI type XII, a recessive form of the disease characterized by several cranial deformities, mild scoliosis, hyperextensibility of the interphalangeal joints and osteoporosis." (PMID 39320469, 2024). "During juvenile stage, sp7 mutants present scoliosis, bone growth defects, ribs fractures and specific craniofacial malformations, resembling human patients’ outcome." (PMID 39320469, 2024).
soft tissue tumors (1 paper, 2021). "Here, we report that expression of NT3 in the mesenchymal lineage with Osterix (Osx/Sp7)-Cre or Fibroblast-Specific Protein 1 (FSP1)-Cre caused subcutaneous, soft tissue tumors." (PMID 34292968, 2021).
infection (12 papers, 2012 to 2025). The state of being infected such as from the introduction of a foreign agent such as serum, vaccine, antigenic substance or organism. "The abundance of half of these serine proteases increased in the haemolymph after both infections, notably cSP48, Hayan, Ser7, SPE and Sp7; the others remained stable, and only ModSP was reduced after infection." (PMID 40223358, 2025). "It follows that flies are protected to some degree from M. robertsii secondary infection in Sp7 mutants through the activation by PAO1 of the PPO/Hayan axis of melanization, which is presumably not affected in Sp7 mutants." (PMID 38833496, 2024). "Infection with wild-type SP7 increased alkaline phosphatase staining (suggesting enhanced osteoblast differentiation) and Alizarin red staining (indicating enhanced bone matrix mineralization)." (PMID 35121733, 2022). "We detected only two differentially expressed canonical immunity genes in samples of day 3 post infection, phenol oxidase-activating factor 2 and proclotting enzyme SP7, serine proteases that were shown to be involved in prophenoloxidase (PPO) activation." (PMID 36536278, 2022). "Recognition receptor genes, SP1 and SP7, were downregulated at 49 h post infection and then upregulated at 84 h, while CTL1 showed the opposite pattern." (PMID 33815150, 2021). "The infection of Runx2-expressing adenovirus into Runx2−/− calvarial cells upregulated Sp7 expression 10 times after 6 hours and 50 times after 12–48 hours compared with that before infection." (PMID 22396760, 2012). "Both wild-type and mutant SP7 protein were expressed at similar levels upon infection, suggesting that the mutation did not affect protein translation or stability." (PMID 35121733, 2022). "Previous studies demonstrated that BALB/c mice chronically infected with two isolates of different virulence transmitted the infection to their progeny only at a very low rate [8 and 17% of total pups, for the higher (Nc-Sp7) and lower virulence (NcSpainH-1) isolate, respectively]." (PMID 33195616, 2020). "We found that several genes implicated in pathogen recognition (NimB1, lectin-24A and Tep2), along with regulators of the Toll (nec, PGRP-SA, SPE and Sp7) and IMD (PGRP-SD and Rel) pathways, are induced following infection." (PMID 35621824, 2022). "The cells were viable at a similar level after the infection of the adenovirus expressing either EGFP, Sp7, or sh-Sp7 at the higher dose." (PMID 22396760, 2012). "While Sp7 activation resulted in PPO1 activation in hemolymph, activated Hayan led to PPO1 and PPO2 activation at the site of injury, indicating separation of the PO system activation pathways in response to injury and infection." (PMID 39941087, 2025). "In contrast, infection with mutant SP7 suppressed both alkaline phosphatase and mineralization, not only compared to wild-type SP7 but also compared to the negative control vector." (PMID 35121733, 2022).